PON3 (paraoxonase 3)
Description:
Has low activity towards the organophosphate paraxon and aromatic carboxylic acid esters. Rapidly hydrolyzes lactones such as statin prodrugs (e.g. lovastatin). Hydrolyzes aromatic lactones and 5- or 6-member ring lactones with aliphatic substituents but not simple lactones or those with polar substituents.
Tractability: Antibody: its Gene Ontology location is reachable by antibodies, with high confidence; UniProt places it where antibodies can reach, with medium confidence; UniProt predicts a signal peptide or a membrane-spanning region. PROTAC: its protein half-life has been measured.
Target class: Enzyme; Hydrolase
Gene: Protein-coding gene on chromosome 7 (95,357,618 to 95,396,493, reverse strand). Ensembl gene ENSG00000105852.
Subcellular location: Secreted, extracellular space
Pathways (Reactome):
Drug ADME: Atorvastatin ADME
Metabolism: Synthesis of 5-eicosatetraenoic acids
Gene Ontology:
Molecular function: acyl-L-homoserine-lactone lactonohydrolase activity; arylesterase activity; protein homodimerization activity; aryldialkylphosphatase activity
Biological process: carboxylic acid catabolic process; lactone catabolic process; regulation of cellular response to drug; response to toxic substance; negative regulation of superoxide anion generation
Cellular component: extracellular exosome; endoplasmic reticulum membrane; extracellular region
Genetic constraint (gnomAD): Loss-of-function variants: 37 observed, 38.78 expected, observed/expected ratio (o/e) 0.95, 90% interval 0.73 to 1.25. The upper end of that interval is the gene's LOEUF score, 1.25, which puts it in group 5 of 6, group 1 being the genes least tolerant of losing a copy. Missense variants: 415 observed, 448.67 expected, observed/expected ratio (o/e) 0.92, 90% interval 0.85 to 1. Synonymous variants: 155 observed, 164.4 expected, observed/expected ratio (o/e) 0.94, 90% interval 0.83 to 1.08.
Homologues: Orthologues: chimpanzee PON3 (100% identical), macaque PON3 (97% identical), mouse Pon3 (81% identical), rabbit PON3 (81% identical), pig PON3 (81% identical), dog PON3 (79% identical), guinea pig PON3 (76% identical), rat Pon3 (75% identical), tropical clawed frog pon2 (55% identical), zebrafish pon2 (50% identical), zebrafish pon1 (50% identical), zebrafish pon3.2 (50% identical), and 6 more. Paralogues in human: PON2 (66% identical), PON1 (60% identical).
Diseases named in the same sentence as PON3 in open-access papers:
PON3 is named in the same sentence as 93 diseases in open-access papers, as found by Europe PMC text mining. Sharing a sentence is not in itself a finding about the gene and the disease. The quoted sentences say what the papers report.
atherosclerosis (19 papers, 2012 to 2026). A disease characterized by the build-up of fatty material and calcium deposition in the arterial wall resulting in partial or complete occlusion of the arterial lumen. "Emerging evidence supports the role of PON1 and PON3 (HDL associated enzyme) in prevention of atherosclerosis." (PMID 31816846, 2019). "Importantly, a low concentration of PON3 in HDL associates with atherosclerosis in patients with type 1 diabetes and autoimmune disease." (PMID 34634315, 2021). "Search strings included combinations of “PON”, “paraoxonase”, “PON1”, “PON2”, and “PON3” together with terms such as “animal models”, “cancer”, “Atherosclerosis”, and “MASLD”." (PMID 41303537, 2025). "The role of PON3 in atherosclerosis has been previously reviewed but there is increasing interest in the role of PON3 in cancer." (PMID 35326240, 2022). "The PON gene family and atherosclerosis related cardiovascular disease and more specifically, the role of PON3 in atherosclerosis, have been thoroughly reviewed." (PMID 35326240, 2022). "They found that the PON3 level was depleted from the HDL of autoimmune disease patients with subclinical atherosclerosis." (PMID 35326240, 2022). "Because patients with human immunodeficiency virus (HIV) tend to develop metabolic complications associated with atherosclerosis and concomitant CAD, PON3 has been of interest in studying the course of this disease." (PMID 35326240, 2022). "Mechanistically, PON3 seems similar to PON2, and transgenic PON3 expression lowers atherosclerosis and adiposity." (PMID 33806594, 2021). "For further characterization of Human PON3 activity against atherosclerosis, gene expression studies have been performed which revealed human PON3 appears in widely distributed tissues." (PMID 31816846, 2019). "Overall, these studies sustain PON3 against atherosclerosis and antioxidant synergistically to be explored for future therapeutics besides its anti-inflammatory function." (PMID 31816846, 2019). "Adult patients with T1DM and subclinical atherosclerosis have decreased levels of the potent antioxidant protein paraoxonase-3 (PON3) and PON3 concentration correlates with the anti-inflammatory function of HDL." (PMID 30922315, 2019). "Taking into consideration these studies, in the present study we examined the dose-dependent effects of caffeine on liver PON1, PON3 and ApoA1 protein levels, and we evaluated a possible relationship between caffeine and atherosclerosis." (PMID 29215336, 2017). "PON2 and PON3 are also able to hydrolyze lactones similar to PON1, and they have also been implicated in the atherosclerosis process." (PMID 25405733, 2014). "The human enzymes paraoxonase-2 (PON2) and PON3 are intracellular enzymes with established antioxidative effects and protective functions against atherosclerosis." (PMID 22666600, 2012). "In conclusion, PON2 and PON3 reduce oxidative stress and inflammation and thus act as central regulators of diseases, including cancer and atherosclerosis." (PMID 22666600, 2012). "In this review, we summarize the most recent findings and discuss the role of PON2/PON3 in atherosclerosis and cancer." (PMID 22666600, 2012). "However, in patients with autoimmune diseases such as systemic lupus erythematosus and type 1 diabetes with subclinical atherosclerosis, PON3 levels in HDL are markedly reduced." (PMID 41303537, 2025). "Evidence suggests that it is implicated in the pathophysiology of CVDs: PON3 can be bound to HDL in the bloodstream, and may decrease atherosclerosis progression as do other members of the PON family." (PMID 37550405, 2023). "PON3, therefore, may be a potential preventive agent against atherosclerosis development provided identification of its lead substances, increasing or decreasing its endogenous levels despite several explorations undertaken at gene/protein levels." (PMID 31816846, 2019).
atherosclerosis (continued). "Notably, reduction in adiposity, atherosclerotic lesions, and monocyte chemoattractant protein-1-(MCP-1) in control and LDL receptor Knock Out (KO) mice overexpressing hPON3 also suggests synergy of PON3 in obesity control and atherosclerosis." (PMID 31816846, 2019). "The paraoxonases (PON) are a group of antioxidant enzymes, termed PON1, PON2, and PON3 that protect lipoproteins and cells from peroxidation and, as such, may be involved in protection against the atherosclerosis process." (PMID 25993297, 2015). "Moreover, in animal models, both PON2 and PON3 have been shown to abrogate the development of atherosclerosis." (PMID 22666600, 2012). "Furthermore, PON3 is depleted from HDL in autoimmune disease patients with atherosclerosis." (PMID 35326240, 2022). "Here we review studies reporting PON2/PON3 deregulations in cancer, summarize most recent findings on their anti-oxidative and antiapoptotic mechanisms, and discuss how this could be used in putative future therapies to target atherosclerosis and cancer." (PMID 22666600, 2012). "In future studies, we will need to investigate the molecular mechanisms, whereby APOA4, LCAT, PON1, and PON3 protect against atherosclerosis in CKD and if improving their levels in HDL will reverse CKD atherosclerosis in model systems." (PMID 34634315, 2021). "Previous studies reported that PON3 attenuates the oxidation of LDL in vitro and that the overexpression of human PON3 decreased atherosclerosis and adiposity in mice." (PMID 25993297, 2015). "In particular, elevated levels of PON3 enhance cholesterol efflux, decrease LDL oxidation, and improve the antioxidant properties of HDL, all of which contribute to slowing the progression of atherosclerosis." (PMID 41303537, 2025). "PON3, on the other hand, may prevent oxidative modification of LDL in atherosclerosis by degrading lipoperoxides in lipoproteins." (PMID 34357353, 2021). "Given their protective functions against atherosclerosis and their yet unidentified roles in kidney disease, APOA4, LCAT, PON1, and PON3 may represent therapeutic targets for CVD in CKD patients." (PMID 34634315, 2021). "The first coverage report governing the alliance of the PON3 gene with serum PON1 activity in systemic lupus erythematosus (SLE) and atherosclerosis risk, did not reveal any significant association with PON3 variants." (PMID 31816846, 2019). "Also, we only investigated ApoA1, PON1 and PON3 enzymes in liver cells; we did not consider other factors that are related to atherosclerosis in the liver or in other tissues such as endothelium and blood." (PMID 29215336, 2017). "Interestingly, PON3, a gene coding the paraoxonase 3 protein thought to inhibit inflammation and LDL oxidation, was up-regulated, while pro-inflammatory C-reactive protein was down-regulated, suggesting an SDA diet of 3.7 g/day in humans may have beneficial effects in atherosclerosis development." (PMID 23598439, 2013).
Obesity (8 papers, 2012 to 2025). Accumulation of substantial excess body fat. "The paraoxonase (PON) gene family (including PON1, PON2, and PON3), is known for its anti-oxidative and anti-inflammatory properties, protecting against metabolic diseases such as obesity and metabolic dysfunction-associated steatotic liver disease (MASLD)." (PMID 39334710, 2024). "When challenged with a Western or CC diet, Pon3−/− mice displayed increased susceptibility to obesity, altered lipid profiles, increased gallstone burden, and exacerbated atherosclerotic lesion development, supporting a role for PON3 in metabolic regulation and vascular protection." (PMID 41303537, 2025). "Additionally, PON3-KO mice were found to be susceptible to obesity." (PMID 39589852, 2024). "Another group of relevant antioxidant enzymes associated with obesity is the paraoxonase family (PON1, PON2, PON3), among which PON1 is the most studied one." (PMID 32752212, 2020). "We found two haplotypes associated with obesity by BMI (in GPX3 and in GPX5 and GPX6) and five haplotypes associated with obesity by PBF (in GPX3, in PON1, and in PON2 and PON3)." (PMID 32752212, 2020). "In this research, three haplotypes; two in PON1, and one PON2 and PON3, were found to be risks factor for obesity." (PMID 32752212, 2020). "The other four haplotypes were associated with obesity when it was classified by BFP; one of them in GPX3, two others in PON1, and the last one in PON2 and PON3." (PMID 32752212, 2020). "A protective role of PON3 in obesity has been demonstrated in vivo in PON3 knockout (PON3−/−) mice." (PMID 41303537, 2025). "Regarding alterations in PON expression in obesity, only one study has been conducted, in pigs, where PON3 mRNA expression in fat tissue was positively correlated with subcutaneous, visceral and total body fat weight, indicating a potential role for PON3 in obesity." (PMID 24562334, 2014). "Moreover, this study showed that elevated human PON3 expression decreased obesity in male mice." (PMID 22824324, 2012). "This analysis identified proteins not previously associated with childhood obesity, to the best of our knowledge, including A2M, PON3, ADAMTSL4, HSPG2 and MAGEB6B, all of which showed decreased levels in children with obesity." (PMID 39972214, 2025). "These parallel results emphasize PON3 as an attractive candidate for future studies in relation to its joint participation in CVD and obesity." (PMID 31816846, 2019). "However, in addition to its anti-atherogenic and anti-obesity effects, PON3 is known to hydrolyze bacterial QS molecules, such as 3OC12-HSL; therefore, it is plausible that the presence of PON3 plays a protective role against bacterial infection." (PMID 22824324, 2012).
coronary artery disease (6 papers, 2015 to 2024). "Serum PON3 is significantly higher in patients with peripheral artery disease or coronary artery disease than control subjects but significantly lower in uremic subjects on HD." (PMID 34634315, 2021). "In the group of female patients with coronary heart disease and in the control group of healthy women genetic variations including the PON1 promoter (-107 C/T, -162 G/A, -831 G/A) and coding region (160 R/G, 192 Q/R,) as well as PON2 311 S/C, and PON3 -133 C/A polymorphisms were evaluated." (PMID 33670025, 2021). "In the past few years, the Paraoxonase multigene family (PON1, PON2, PON3) has been shown to play an important role in pathogenesis of cardiovascular disorders including coronary artery disease (CAD)." (PMID 31816846, 2019). "The next studies evaluating these same six SNPs performed by the same authors in patients with HIV and with coronary artery disease (CAD) did not reveal any significant impact of the PON3 genotype on the serum PON3 level." (PMID 33670025, 2021).
diabetes (5 papers, 2019 to 2025). "Gal-4 and PON3 remained significantly associated with incident diabetes after adjusting for plasma glucose, implying a glucose independent association with diabetes." (PMID 30670722, 2019). "Three proteins, lipoprotein lipase, IGF-binding protein 2 and paraoxonase 3 (PON-3), were inversely associated with diabetes." (PMID 31446444, 2019). "Only PON3 remained significantly associated with decreased risk of diabetes." (PMID 30670722, 2019). "Furthermore, we identified novel associations for CTSD, Gal-4 and PON3 with incident diabetes." (PMID 30670722, 2019). "Only three proteins were associated with lower odds of diabetes, i.e. lipoprotein lipase (LPL), IGF-binding protein 2 and paraoxonase 3 (PON-3)." (PMID 31446444, 2019). "All these findings are in line with the diabetes protective effects of PON3 seen in our study." (PMID 30670722, 2019). "When further adjusting for established risk factors (model 2), all 7 proteins remained significantly associated with incident diabetes; 5 proteins (CD163, Gal-4, CTSD, PAI and FABP4) with an increased risk of diabetes and 2 proteins (PON3 and IGFBP-2) with a decreased risk for incident diabetes:." (PMID 30670722, 2019). "In total there were 44 out of 973 (4.5%) proteins that contributed significantly to the prediction of diabetes (FDR-corrected p<0.05) in the random forest model, the most important being NOS3, HGF, PON3, IGSF3, and ADGRG1." (PMID 33279861, 2021).
liver disease (5 papers, 2014 to 2025). "PON3 has hepatoprotective properties, preventing histological changes and liver cell apoptosis associated with liver disease." (PMID 41303537, 2025). "PON3 has also been shown to have hepatoprotective effects, preventing histological alterations and hepatocyte apoptosis that leads to liver disease." (PMID 39641443, 2024). "PON3 has also been shown to have a hepatoprotective role that prevents histological changes and liver cell apoptosis, which leads to liver disease." (PMID 35326240, 2022). "The protective role of PON3 in liver disease is expected since paraoxonases have a protective role against oxidative stress, which plays an important role in the pathogenesis of liver disease." (PMID 35326240, 2022). "Also, the present study suggests that PON1, PON3, and PPAR-δ had protective roles against liver disease." (PMID 25478064, 2014). "PON3 (serum paraoxonase/lactonase 3), which was upregulated exclusively in LSSD-CHB, might play a hepatoprotective role against histological alterations and hepatic cell apoptosis leading to liver disease." (PMID 28025641, 2016).
autoimmune disease (4 papers, 2020 to 2022). A disorder resulting from loss of function or tissue destruction of an organ or multiple organs, arising from humoral or cellular immune responses of the individual to their own tissue constituents. "Increased serum PON3 protein concentration has been reported in chronic liver disease, HIV infection, and atherothrombotic disease and in patients with sepsis, while a decrease of PON3 concentration has been detected in certain autoimmune diseases." (PMID 33505588, 2021).
esophageal cancer (4 papers, 2018 to 2024). A primary or metastatic malignant neoplasm involving the esophagus. "In models of multi-drug resistant esophageal cancer, in vitro studies showed that PON3 is hypermethylated at the promoter region, which consequently downregulates its expression." (PMID 35326240, 2022). "Further in vitro studies using the K150 cell line transfected with GFP-PON3 revealed that PON3 suppressed migration and invasion of esophageal cancer cells." (PMID 35326240, 2022). "We performed the wound-healing and invasion assays to test the effect of the paraoxonase gene PON3 on esophageal cancer (EC) cells." (PMID 30386177, 2018). "Studies have shown that PON3 can inhibit the migration and invasion of esophageal cancer cells, and inhibition of PON3 can significantly reduce the in vitro proliferation and metastasis of oral squamous cell carcinoma cells and slow down the progression of oral squamous cell carcinoma." (PMID 39641443, 2024). "In patients with stage IV esophageal cancer CYCS (p = 0.014), PON3 (p = 0.14), ACPP (p = 0.047), and RPL22 (p = 0.047) were significantly upregulated compared with patients with early-stage cancer." (PMID 33828156, 2021).
hepatocellular carcinoma (4 papers, 2016 to 2024). A malignant tumor that arises from hepatocytes. "A meta‐analysis showed that PON3 was down‐regulated in hepatocellular carcinoma, renal clear cell sarcoma, ovarian serous papillary carcinoma, cervical cancer, papillary thyroid carcinoma, prostate cancer, and non‐Hodgkin lymphoma and up‐regulated in lung adenocarcinoma and pancreatic cancer." (PMID 39641443, 2024). "Furthermore, studies of the relationship between PON3 and hepatocellular carcinoma (HCC) have demonstrated that PON3 inhibits cell proliferation, and downregulation of PON3 contributes to HCC disease progression." (PMID 35326240, 2022).
Alzheimer disease (3 papers, 2023 to 2025). A progressive, neurodegenerative disease characterized by loss of function and death of nerve cells in several areas of the brain leading to loss of cognitive function such as memory and language. "However, this also represents a key strength of the study, as we are the first to investigate serum PON3 in the context of Alzheimer’s disease and its association with MPO." (PMID 39456469, 2024). "In conclusion, our study is the first to explore serum PON3 in the context of Alzheimer’s disease (AD) and mild cognitive impairment (MCI) and to compare its pattern with PON1-arylesterase activity." (PMID 39456469, 2024). "Despite the potential significance of PON3 in Alzheimer’s disease pathology and its functional similarities to the extensively studied PON1, no human studies have investigated whether changes in peripheral PON3 levels are associated with the disease." (PMID 39456469, 2024). "PON1 has been extensively studied in relation to Alzheimer’s Disease (AD), but the role of PON3 remains unknown." (PMID 39456469, 2024). "This study showed the localization of PON-1 and PON-3 around and inside Aβ plaques in a murine model of Alzheimer’s disease (AD), suggesting that HDL particles carry PON-1 and PON-3 from the liver, where they are synthesized to areas of high levels of inflammation and oxidative stress." (PMID 37108044, 2023).